HIF1A (hypoxia inducible factor 1 subunit alpha)
Diseases named in the same sentence as HIF1A in open-access papers (continued):
Sharing a sentence is not in itself a finding about the gene and the disease.
COVID-19 (continued). "Our data from network pharmacology also suggested that five signaling pathways including TNF, HIF-1α, TLR, apoptosis-related, and VEGF signaling may be the therapeutic pathways in Quercetin treatment to COVID-19-induced AKI." (PMID 33444408, 2021). "Therefore, HIF-1α plays an important role in promoting SARS-CoV-2 infection and inducing pro-inflammatory responses to COVID-19." (PMID 34408131, 2021). "Correspondingly, HIF1a is involved in ALI (Acute Lung Injury), an inflammatory lung pathology considered to represent mild ARDS, changes in which are characteristic of complicated COVID-19 cases." (PMID 33163005, 2020). "Based on this, HIF-1α activated by SARS-CoV-2 could elevate the expression of CD147 and this hypothesis can encourage researchers to consider it in future studies, opening a new window to find a new therapeutic approach for cancer patients with COVID-19." (PMID 37016434, 2023). "The top 10 of 41 potential anti-COVID-19 core targets (AKT1, TNF, HSP90AA1, IL-6, mTOR, EGFR, CASP3, HIF1A, MAPK3, and MAPK1) were identified as molecular targets of key active phytonutrients of the Meliae cortex that might be implicated in ameliorating COVID-19." (PMID 36817449, 2023). "Interestingly, it has been shown that both blood cells from COVID-19 patients and SARS-CoV-2 infected cells, in normoxia condition, accumulate hypoxia-inducible factor 1α (HIF-1α), eliciting inflammatory responses such as induction of chemokines and secretion of cytokines." (PMID 37884975, 2023). "Furthermore, it could effectively reduce acute lung injury by regulating the expression of pulmonary inflammatory factors p-p38 MAPK, NF-κB 65, HIF-1α, p-IκB-α, and TGF-β1 and improve dyspnea and hypoxemia in patients with severe COVID-19." (PMID 35035505, 2022). "A better understanding of the mechanisms of HIF-1α stabilization/degradation and molecular crosstalk between HIF-1α and other cellular proteins will likely suggest new targets and new therapeutic strategies that may help to overcome COVID-19." (PMID 36091390, 2022). "Indeed, a transcriptomic analysis of lung tissue from COVID-19 patients found up-regulation of HIF-1α and inflammatory cytokines but not type I IFN." (PMID 34108245, 2021). "Therefore, HIF-1α is a key activator for both SARS-CoV-2 infection and inflammatory response, thereby serving as a potential therapeutic target for virus-induced inflammatory diseases and COVID-19." (PMID 34408131, 2021). "Therefore, HIF1A expression by monocytes could serve as a biomarker for the severity of COVID-19 even in convalescent patients without residual disease symptoms 2 weeks after infection." (PMID 38391913, 2024). "Preventing transactivation of HIF-1α by peptide inhibitors of HIF-1/CBP-p300 interaction (previously shown to suppress tumor growth) or other compounds with similar effects, could be interesting to test in order to evaluate their possible benefit in the treatment of COVID-19." (PMID 36091390, 2022). "HIF-1α can regulate the activity of genes related to glucose transport and processing (LDH-A, PFKFB3, GLUT-1, PKM2), which seems to be overexpressed in monocytes from COVID-19 patients, but not at the same intensity as influenza virus and RSV-infected monocytes." (PMID 33716771, 2021).
neuroblastoma (126 papers, 2007 to 2025). Neuroblastoma (NB) is the most common solid, extracranial childhood tumor. "Together with HIF-1α, another transcription factor associated with poor neuroblastoma prognosis, MYC proteins are known to affect mitochondrial biogenesis and metabolism." (PMID 37973789, 2023). "Both DOXY-sel cell lines exhibited downregulation of several proteins associated with poor neuroblastoma prognosis, including HIF-1α, P-gp, or MCL-1." (PMID 37973789, 2023). "To analyse the relation between HIF1A expression and differentiation-related genes in high-risk neuroblastoma patients, we looked into gene expression data from the TARGET database." (PMID 34557995, 2022). "We further analysed the expression of differentiation-related genes (SYP, NEFL, ENO2, MAPT) in high-risk neuroblastoma patients and correlated them to HIF1A expression." (PMID 34557995, 2022). "AQP1 and HIF-1α have also been associated with invasiveness and migration in neuroblastoma and other cancers as well as with resistance to chemotherapy." (PMID 33644043, 2021). "More recently, the sonic hedgehog signaling pathway has been implicated in HIF-1α-mediated proliferation and invasion of neuroblastoma cells." (PMID 26475688, 2015). "Both gain-of-function and loss-of-function studies showed that HIF-1α affected the chemotactic migration of PDAC cells toward supernatants of activated neuroblastoma (conditioned supernatants) and CX3CL1." (PMID 22952674, 2012). "Two allelic forms (wt = wild type, p.P582S = rare variant) of HIF-1α expression vector were co-transfected with pHRE in separate experiments using SK-N-FI (neuroblastoma) cell line." (PMID 19691832, 2009). "Several studies about neuroblastoma that was also prevalent in children have also identified an association between high HIF-1α and low tumor stages, as well as better prognosis, which supported the potential protective effect of the high expression of HIF-1α in ACP patients." (PMID 36091021, 2022). "For instance, P2X7R blockade diminished VEGF levels in a HIF-1α-dependent manner, which hindered neuroblastoma progression." (PMID 41034696, 2025). "Knockdown of endogenous p4htm in neuroblastoma cells has been shown to increase HIF-1a protein levels in normoxia, and p4htm is induced by hypoxia in a cell type-specific manner." (PMID 39582684, 2024). "Knockout of Usp29 significantly prolongs the survival of tumor-bearing mice by reducing the expressions of MYC and HIF1α in neuroblastoma and B-cell lymphoma." (PMID 39664521, 2024). "Coffee was found to induce VEGF expression in human neuroblastoma SH-SY5Y cells through the activation of HIF-1α, which was related to the inhibition of prolyl hydroxylation independent of caffeine or caffeic acid." (PMID 39594520, 2024). "DJ-1 deficiency reduces HIF-1α expression in neuroblastoma cells, and its regulation of the DJ-1/PI3K/AKT pathway impacts HIF-1α protein expression and transcriptional activity." (PMID 39408813, 2024). "HIF1α-driven transcriptional response in hypoxia in pediatric neuroblastoma is subject to epigenetic control via DNA methylation status of gene regulatory regions." (PMID 38279330, 2024). "Neuroblastoma has notable differential expression of the oxygen-sensitive HIFα subunits (HIF-1α and HIF-2α) at the protein level." (PMID 38474195, 2024). "We previously reported that acrolein activated AP-1 and NF-κB in mouse neuroblastoma Neuro-2a cells, and HIF-1α has also been reported to be induced by acrolein." (PMID 37511605, 2023). "Further studies are needed to explain HIF-1α’s role in retinoid therapies and neuroblastoma treatment." (PMID 34557995, 2022). "Herein, we discuss the involvement of PI3K/Akt during transient and prolonged ischemia, as well as during the restoration of glucose concentration in the human neuroblastoma cell line (SH-SY5Y) together with its crosstalk with HIF-1α and Ca2+." (PMID 35163310, 2022).
neuroblastoma (continued). "In this study, we evaluated the role of HIF-1α in RA-induced differentiation in neuroblastoma cells of the lineage SH-SY5Y under normoxic conditions." (PMID 34557995, 2022). "This work aims to investigate the effects of the selective inhibition of HIF-1α on the differentiation induced by retinoic acid in human neuroblastoma cells from the SH-SY5Y lineage to clarify its role in cell differentiation." (PMID 34557995, 2022). "HIF-1α silencing was able to significantly change the morphology of retinoic acid-treated neuroblastoma cells and reduce the expression of differentiation markers." (PMID 34557995, 2022). "IHC study revealed a positive correlation between SHMT2 and HIF-1α protein expression in human neuroblastoma tissues." (PMID 34359884, 2021). "Beta-carotene mediates its therapeutic effects on human neuroblastoma, including the inhibition of cancer stemness and metastasis, by suppressing the enzyme activity and expression of MMPs, as well as the expression of HIF-1α and its downstream targets." (PMID 33494738, 2021). "In MYC-amplified neuroblastomas, the correlation between SHMT2 and HIF1α was associated with poor patient prognosis, confirming the essential role of HIF1-induced SHMT2 regulation in maintaining therapy-resistant hypoxic cell survival." (PMID 33801846, 2021). "Since HIF1α is a transcription factor, we next asked if peroxides play indispensable role in HIF-dependent transcription by examining Eno2 and Bnip3 mRNA expression levels, which are two established HIF1α target genes, in neuroblastoma SH-SY5Y cells." (PMID 34596045, 2021). "PRO has been shown to inhibit growth, decrease vessel density and lower VEGF, MMP2/9 levels in neuroblastomas and repress tumor growth in hemangiomas through hypoxia-inducible factor-1 alpha (HIF-1α) and STAT3 signaling." (PMID 34790909, 2021). "Our data suggest that expression of AQP1 is linked to HIF-1α as well as HIF-2α and that this hypoxia-related profile is linked to migratory processes in neuroblastoma." (PMID 33644043, 2021). "Another P2X7R antagonist, named AZ10606120, was found to execute growth-inhibitory effect in neuroblastoma through PI3K/GSK3β/hypoxia-inducible factor 1-alpha (HIF-1α) pathway downregulation." (PMID 32280302, 2020). "It was proven that BDNF promotes the expression of a strong pro-angiogenetic factor, VEGF via HIF-1α in neuroblastoma cells." (PMID 32183322, 2020). "This has been validated in neuroblastoma where it was shown that HIF-1α can induce HIF-1α/hypoxia specific DNA methylation signatures." (PMID 32292719, 2020). "Targets of HIF1-α include proteins involved in invasion, intravasation, adhesion and extravasation and these are likely to be responsible for the change in the neuroblastoma cells to a metastatic phenotype." (PMID 31235824, 2019). "In this study, we conducted a combined analysis of RNA expression and DNA methylation of neuroblastoma cells silenced or unsilenced for HIF1A expression, grown in normoxia and hypoxia conditions." (PMID 30808328, 2019). "Here, our aim was to establish a HIF1A-based method useful in the investigation of undiscovered mechanisms of neuroblastoma tumorigenesis under hypoxic microenvironments." (PMID 30808328, 2019). "A HIF1α-to-HIF2α switch has been previously observed, notably in neuroblastoma cells exposed to prolonged hypoxia, but the mechanism behind the switch remains elusive." (PMID 29993038, 2018). "In neuroblastoma, HIF1α is stabilized rapidly in response to hypoxia, mediating the acute cellular response to oxygen deprivation, whereas HIF2α accumulates later and mediates the chronic effects of hypoxia." (PMID 29993038, 2018). "It is known that suppressing HIF-1α, with low-dose topotecan, potentiates the effects of the antiangiogenic drugs in mouse models of neuroblastoma and GBM." (PMID 29262591, 2017).
neuroblastoma (continued). "HIF-1α, HIF-2α expression is detected in undifferentiated neuroblastoma cells however HIF-1α expression appears to be dominant and HIF-2α induction was only observed in certain cells under complete anoxia (0% O2)." (PMID 28968430, 2017). "Neuroblastoma cell lines were shown to stabilize HIF-1α in hypoxia and to up-regulate hypoxia-responsive genes, including VEGF." (PMID 26393682, 2015). "Knock-down of HIF1α reduced growth in combination with anti-angiogenic therapy in neuroblastoma xenografts." (PMID 25700172, 2015). "In the current study, similar to Nultin-3a, we observed that RG7388 treatment of neuroblastoma cells leads to a decrease in HIF-1α and VEGF mRNA and protein expression." (PMID 26998348, 2015). "In neuroblastoma, HIF-2α predicts poor patient outcome, while HIF-1α has been associated with a favorable prognosis." (PMID 26475688, 2015). "They reported that the inhibition of PI3K with LY294002 decreases HIF-1α protein expression significantly in neuroblastoma cell lines." (PMID 24759734, 2014). "First, the capacity of the four compounds to induce HIF-1α stabilization and nuclear translocation in the human neuroblastoma cell line SH-SY5Y was analyzed using microscopic analysis and Cellomics ArrayScan quantification." (PMID 25006572, 2013). "Our results suggest that HIF-1α plays a marked role in suppressing retinoic acid-induced differentiation of neuroblastoma cells exposed to intermittent hypoxia." (PMID 22363512, 2012). "In support of this, BDNF activation of TrkB has been found to induce vascular endothelial growth factor (VEGF) expression via hypoxia inducible factor-1-alpha (HIF-1-α) in neuroblastoma cells." (PMID 21767406, 2011). "The role of HIF2α should be of particular interest in view of its strong expression in hypoxic neuroblastoma cells relative to HIF1α and its expression in chromaffin cell types." (PMID 20862257, 2010). "Down-regulation of HIF-1α by shRNA interference was also shown to reduce hypoxia-induced resistance of neuroblastoma cells against etoposide and vincristine." (PMID 20626868, 2010). "The strikingly similar distribution of immunoreactivity for HIF1α and HIF2α in neuroblastoma supports the validity of our hypoxia markers." (PMID 20862257, 2010). "Nuclear immunoreactivity of HIF1α coincided with that of HIF2α in all neuroblastoma xenografts, albeit with lower intensity which was particularly evident in tumors derived from Kelly cells." (PMID 20862257, 2010). "This fact prompted us to analyze the expression patterns of HIF-1α in the SK-NF-I human neuroblastoma and CCF-STTG1 human astrocytoma cell line." (PMID 19653907, 2009). "In order to directly monitor the transcriptional activity of HIF-1α in neuroblastoma cells, we generated a luciferase reporter vector containing multiple hypoxia responsive elements inserted in the SV40 strong promoter." (PMID 19653907, 2009). "Interestingly, in a previous study the different roles of HIF1α and HIF2α in neuroblastoma with regard to MYCN status and hypoxia was addressed." (PMID 41118218, 2025). "GRP-R regulates glucose metabolism in neuroblastoma by modulating HIF-1α, PDK4, and PDP2." (PMID 40746885, 2025). "In addition, hypoxia has been reported to play a role in regulating neuroblastoma differentiation, and Hypoxia-Inducible Factor 1-alpha (HIF1α) is capable of binding to the SLIT3 promoter." (PMID 40448172, 2025). "Notably, the main conclusion from that study was that it was HIF1α which was predominantly expressed in MYCN-amplified neuroblastoma cells and primary tumors." (PMID 41118218, 2025). "Hypoxia exposure induces global DNA hypermethylation in neuroblastoma cells, and HIF1A itself might control DNA methylation." (PMID 38279330, 2024). "Other studies showed downregulation of ENO2 in a neuroblastoma cell line with silencing of HIF-1A." (PMID 39567394, 2024).
neuroblastoma (continued). "Previous reports demonstrated that Id2 is a direct transcriptional target of HIF-1α in neuroblastoma cells, suggesting that HIF-1α and ID2 may function in a feed-forward loop in HSCs." (PMID 35775482, 2022). "HIF-1α role in neuroblastoma cells differentiation treatment is ambiguous." (PMID 34557995, 2022). "Interestingly, SYP and TAU mean expression was elevated in HIF1A High Expression neuroblastoma patients." (PMID 34557995, 2022). "HIF1A is involved in Retinoic Acid (RA) induced differentiation in SH-SY5Y neuroblastoma cells." (PMID 34557995, 2022). "In addition, cells were co-stained for the glial marker GFAP, as previous findings reported glial trans-differentiation induced by retinoic acid in HIF-1α inhibited neuroblastoma cells." (PMID 34557995, 2022). "High TRPM2 expression significantly enhanced expression of α1, αv, β1 and β5 integrins in the membrane of neuroblastoma cells and integrin complex formation, through transcriptional mechanisms including increased HIF-1α, E2F1, and FOXM1, resulting in promotion of migration and invasion." (PMID 36446940, 2022). "In addition, the initiation of hypoxia and induction of HIF-1α can increase the acetylation of H3 and H4 in neuroblastoma cells and increases the aggressiveness of neuroblastomas." (PMID 33585477, 2021). "Similarly, high levels of N-MYC in N-MYC amplified neuroblastoma cells override HIF1α inhibition of cell cycle progression under hypoxia and cooperates with HIF1α to promote the expression of phosphoglycerate kinase 1 (PGK1), HK2, and LDHA." (PMID 33251216, 2020). "Furthermore, loss of DJ-1, an autosomal recessive gene for familial PD, was shown to provoke hypoxic condition and increase reactive oxygen species production in human neuroblastoma cell, which in turn stabilized the HIF-1α." (PMID 32377332, 2020). "However, the fact that HIF-1α induction is seen in human neuroblastoma cells and primary rat neurons is sufficient to imply that this induction is likely to occur in normal human neurons." (PMID 28590414, 2017). "For example, targeting HIF1α increases the efficacy of bevacizumab in neuroblastoma xenografts." (PMID 27153561, 2016). "Altered lncRNA expression influenced the levels of HIF-1α mRNA and protein in neuroblastoma cells." (PMID 27824082, 2016). "However, growth factor signaling has been shown to regulate HIF1α at both the transcriptional and translational level, and HIF2α transcription in hypoxic neuroblastoma cells is regulated by IGF-2." (PMID 26849233, 2016). "Our results support that intermittent hypoxia could expand selectively stem-like subpopulation in the neuroblastoma cells in part through upregulation of HIF-1α and HIF-2α." (PMID 22363512, 2012). "In addition, BDNF is upregulated by hypoxia through HIF-1α and promotes angiogenesis, as described in neuroblastoma models." (PMID 21966426, 2011). "Furthermore, HIF1A mean expression was not altered either among deceased and alive patients or High-risk and Low-risk neuroblastoma patients." (PMID 34557995, 2022). "Understanding how HIF-1α influences cell proliferation and differentiation may provide the basis for better comprehension of its influence in retinoid therapies for the treatment of neuroblastoma." (PMID 34557995, 2022). "Oxygen levels may regulate retinoic acid-HIF-1α’s influence in neuroblastoma cells differentiation." (PMID 34557995, 2022).